LINC01019 (long independently transcribed non-coding RNA 1019)
Synonyms: uc.150; LINC01017
Gene: Long non-coding RNA gene on chromosome 5 (3,357,264 to 3,536,102, reverse strand). Ensembl gene ENSG00000248118.
Diseases named in the same sentence as LINC01019 in open-access papers:
LINC01019 is named in the same sentence as 2 diseases in open-access papers, as found by Europe PMC text mining. Sharing a sentence is not in itself a finding about the gene and the disease.
LINC01019 shares sentences with these, for which no sentence is quoted: lung carcinoma (1 paper); nasopharyngeal carcinoma (1).